BARD1 (BRCA1 associated RING domain 1)
Diseases named in the same sentence as BARD1 in open-access papers (continued):
Sharing a sentence is not in itself a finding about the gene and the disease.
cancer (continued). "Recently cancer-associated germline patient variants in the BARD1-RING have been described which do not reduce BRCA1-BARD1 ligase activity, but do specifically prevent ubiquitination of H2A." (PMID 31552267, 2019). "BARD1 is included in several gene sequencing panels currently marketed for the prediction of risk of cancer, however there are no gene-specific guidelines for the classification of BARD1 variants." (PMID 31803232, 2019). "Due to insufficient evidence of a BARD1 association with BC risk, BARD1 was not included in the recently proposed consensus multigene panel by the UK Cancer Genetics Group for BC testing." (PMID 31142030, 2019). "Cancer-related isoforms of BARD1, except for FLBARD1, can result in proliferation arrest in vitro." (PMID 30975222, 2019). "At the time of this discovery, it was recognized that BARD1 bound BRCA1, though the role for BARD1 as a cancer predisposition gene was previously unknown." (PMID 30200332, 2018). "However, the repression of FL BARD1, as it is the case in many types of cancer, favors expression of BARD1δ." (PMID 28030839, 2017). "These discordant results might be due to population substructure or gene modifiers affecting the role of BARD1 in cancer development." (PMID 29292755, 2017). "Down-regulation of FL BARD1 can have oncogenic effects whereas BARD1 isoforms that lack RING or/and ANK domains are often up-regulated and associated with negative prognosis in breast, ovarian endometrial and lung cancers." (PMID 29292755, 2017). "The cancer specific BARD1 isoforms with diverse tertiary structures might present immunogenic BARD1 epitopes." (PMID 28786985, 2017). "BARD1δ was first identified as a BARD1 isoform upregulated in a rat cancer cell line NuTu-19 which was derived from spontaneously transformed rat ovarian cells, suggesting this isoform of BARD1 and its cancer-associated functions are conserved between human and rat." (PMID 28030839, 2017). "The role of BARD1 in the development and progression of proliferative lung diseases other than cancer remains unknown." (PMID 26415510, 2015). "Hypoxia is also a driver of miRNA expression in cancers and could play an additive role on the regulation of BARD1 expression, as BARD1 upregulation was observed in response to hypoxia in vivo." (PMID 26415510, 2015). "The interlinked network of BRCA1/BARD1, RHAMM, Aurora A, and TPX2 is important for efficient apicobasal polarity of epithelial cells, and disruption of this through altered microtubule dynamics or altered mitotic spindle can increase the risk of cancer." (PMID 24278741, 2012). "BARD1 seems a plausible target for female-specific cancer and other cancer studies." (PMID 23056176, 2012). "The BARD1 c.2229dupT variant generates a premature termination codon (PTC), affecting the BCRT 2 domain, which is involved in protein-protein interactions and has been linked to DNA repair, recombination, and cell cycle control—mechanisms critical in the development of malignant neoplasms." (PMID 40458721, 2025). "BRCA1 associated RING domain 1 (BARD1) has often been thought of as a tumor suppressor gene, but recent studies have caused some to re-evaluate its cancer-related role as being oncogenic instead, with the gene having potential as a therapeutic target for cancer susceptibility and testing." (PMID 38442712, 2024). "Notably, several BARD1 isoforms lacking exon 3, such as BARD1β (lacking exons 2 and 3) and BARD1δ (lacking exons 2–6), antagonize full-length BARD1 and confer cancer susceptibility and oncogenicity." (PMID 38485918, 2024). "Thus, as in C. elegans, human BRCA1 and BARD1 are not equivalent in function leading to different spectrum of cancers when mutated." (PMID 36716349, 2023). "In addition, BARD1 is being investigated as a potential therapeutic target for cancer treatment." (PMID 37727789, 2023).
cancer (continued). "In addition, RNA-sequencing analysis revealed that loss of BARD1 results in the upregulation of GBP1 (guanylate-binding protein 1), a protein whose expression is associated with variable response to therapy depending on the adult carcinoma subtype examined." (PMID 36187937, 2022). "Interestingly, BARD1 splice isoforms, which lack the RING domain, such as BARD1-β and -δ, show effects that are antagonistic to that of BARD1-FL, and have been associated with progression and poor prognosis in multiple cancer types." (PMID 33672422, 2021). "The clinical impact of BARD1 dysfunction in cancer cells is currently unknown." (PMID 32726901, 2020). "Indeed, BARD1 was added to gene testing panels not long after it was proposed as a cancer predisposing gene." (PMID 32726901, 2020). "Significantly, we observed locus-specific retention of hydroxymethylation marks in specific intronic and intergenic regions which may play a novel role in the regulation of gene expression in critical functional pathways, such as BARD1 signaling and steroid hormone receptor signaling in cancer." (PMID 26981160, 2016). "However, overexpressed aberrant isoforms rather than mutations of BARD1 have been reported in cancer." (PMID 24349422, 2013). "A significant advance in understanding the physiologic importance of the BRCA1: BARD1 interaction was the finding that the BRCA1: BARD1 heterodimer functions as an E3 ubiquitin ligase and that this ubiquitin ligase activity was abolished by cancer-associated mutations within the BRCA1 RING domain." (PMID 23802008, 2013). "However, curiously, some of the cancer-associated mutants of BARD1 do not alter the function of BARD1 in HDR." (PMID 23802008, 2013). "On the other hand, various BARD1 isoforms that lack functional domains, such as the RING-finger and ANK domains due to exon skipping, have been found to be upregulated in different cancers." (PMID 40805222, 2025). "Several reports suggest that alternative splicing of specific genes, such as BRCA1, BRCA2, BARD1, or ERCC1, can impact on the response of cancer cells to PT and some studies also suggest that this correlates with PT resistance in human cancer." (PMID 32332923, 2020). "On the other hand, several BARD1 isoforms resulting from alternative splicing that lack RING-finger and/or ANK domains were upregulated in different cancers and are suggested to have an oncogenic effect by antagonizing the function of full-length BARD1." (PMID 32679805, 2020). "FGF2 and CHEK4 are up-regulated while the expression of CHEK1, WT1, MDM2, BARD1, BMP2, BAMBI, and SOD2, have been reported to be down-regulated in several cancer subtypes, including CRC." (PMID 31623294, 2019). "Last but not least, we provide an example on the applicability of an Arabidopsis thaliana—based plant system monitoring the role of cancer-related DNA repair genes BRCA1, BARD1 and PARP1 in processing DNA lesions." (PMID 28587301, 2017). "Moreover, some BARD1 isoforms were expressed in both cancer and adjacent healthy tissues, leading to the conclusion that isoform expression could be involved in the initiation of tumorigenesis, thus ‘marking’ an early step of cancer progression." (PMID 24349422, 2013). "In BTBD2-BARD1, BARD1 was suggested as a mediator of apoptosis since its over-expression induces cell death; and high LOH has been detected in human carcinoma metastases to the brain at chromosome 19p13.3 for BTBD2." (PMID 23940583, 2013). "Transcriptional profiling followed by ChIP identified a subset of cellular genes that are regulated in a similar fashion to HIV-1 by Spt6 and/or PAAF1, including many that are involved in cancer, such as BRCA1 and BARD1." (PMID 22316138, 2012). "Each case carried VUS in genes related to DNA repair (POLD1, BARD1, or BRIP1); however, given the uncertain classification of these variants, no direct inference regarding hereditary cancer predisposition can be made." (PMID 41595443, 2025).
cancer (continued). "During the study period, moderate cancer risk genes such as ATM, CHEK2, and BARD1 were not analyzed in Denmark." (PMID 40408052, 2025). "The relevance of the BRCA1/BARD1 ubiquitin E3 activity for HR in terms of DNA DSB repair and treatment resistance remains contradictory in current literature, due to the use of different approaches involving diverse cancer cell lines and models." (PMID 38769345, 2024). "Overexpression of BARD1 isoforms can have distinct, non-redundant effects on cell proliferation and cancer." (PMID 38539439, 2024). "The early disease onset and having two cancers in this case may be the result of harboring two PVs in BRCA2 and BARD1 genes." (PMID 34646395, 2021). "BARD1 was significantly enriched in both the case-control analyses (non-cancer east-Asian population and with non-cancer females) and against the French cohort." (PMID 32566746, 2020). "Cancer-derived variants of BRCA1, BARD1, OLA1, and RACK1 failed to interact, and aberrant expression of these proteins caused centrosome amplification due to centriole overduplication only in mammary tissue-derived cells." (PMID 32722046, 2020). "Although p50 bound BARD1 mutated at residues outside the BRCT domains (C557S and Q564H), p50 did not bind BARD1 with cancer-associated mutations within the BRCT domains (R658C and S761N)." (PMID 33024116, 2020). "Although previous cancer research showed that the majority of BRCA1 proteins form a heterodimer with BARD1, BARD1 did not colocalize with BRCA1 in tau aggregates in the AD, PiD, and PSP brain samples." (PMID 31861888, 2019). "The binding of C-terminal fragment of BARD1 to the ANK repeats domain of BCL3, a NF-κB inhibitor in vitro, may affect the correct regulation of NF-κB in cancer and inflammatory and autoimmune diseases." (PMID 29292755, 2017). "Consistent with its pro-proliferative action BARD1β was found expressed in most epithelial cell-derived cancers, but in combination with other isoforms and absence of FL BARD1." (PMID 26415510, 2015). "We have shown previously that BARD1β promotes cancer cell proliferation and induces proliferation of non-transformed fibroblasts, we wanted to monitor the specific expression of FL BARD1 and BARD1β in response to TGF-β treatment." (PMID 26415510, 2015). "The time-dependent reduction of these truncated BARD1 isoform(s) after Vorinostat stimulation was also observed in Kelly and MCF7 cells, but not in HeLa cells, suggesting that a restricted panel of cancer cells displays BARD1 deregulation." (PMID 24349422, 2013). "While this mechanism remains to be validated in cancer, this finding raises the possibility that histone marks not only affect BARD1 expression levels but may also drive isoform heterogeneity." (PMID 41009605, 2025). "For example, low expression of BARD1 in HNSC shows a significant correlation with patient survival, suggesting that high expression functions in some way as a positive factor for cancer, whether promoting growth, evasion of the immune system, or resistance to genotoxic agents." (PMID 35950764, 2022). "The identification of BARD1 PV carriers should be taken with caution, as inherited PVs in moderate- to low-penetrance genes may not necessarily be responsible for all the cancer diagnoses in a family." (PMID 33498765, 2021). "No BARD1 PVs were identified in our set of 194 cancer-free individuals." (PMID 33498765, 2021). "Importantly, the cancer-predisposing C61G mutation in BRCA1, which abrogates its E3 ubiquitin ligase activity, and disrupts the BRCA1 RING domain and its interaction with BARD1, did not significantly alter the frequency of fusions induced by TRF2 depletion." (PMID 25582120, 2015). "However, it seems that in such cells, nuclear import of BRCA1/BARD1 is impaired rather than nuclear export of BARD1, thereby explaining its cytoplasmic accumulation and thus cancer development." (PMID 26402707, 2015).
cancer (continued). "Thus, our study not only identifies BARD1 mutations affecting the BRCA1/BARD1 complex but also uncovers the synergetic effect of cis mutations in individual genes on tumorigenesis, which updates the understanding of how non-effective mutations cause cancers." (PMID 33623049, 2021). "As pathogenic BRCA1 variants located in the RING domain disrupt BARD1-BRCA1 interaction, it was hypothesized that variants in BARD1 may also affect this interaction, thereby making BARD1 an attractive candidate to pursue in BRCA1 mutation negative cancer families." (PMID 32726901, 2020).
infection (1 paper, 2019). The state of being infected such as from the introduction of a foreign agent such as serum, vaccine, antigenic substance or organism. "However, only BARD1 protein was changed after LV-210 or LV-In-210 infection." (PMID 30760709, 2019).
BARD1 also shares sentences with these, for which no sentence is quoted: hereditary ovarian cancer (3 papers); meningioma (3); Breast and (2); glioblastoma (2); glioma (2); hereditary breast and ovarian cancer syndrome (2); hereditary colorectal cancer (2); mesothelioma (2); osteosarcoma (2); rhabdomyosarcoma (2); adenocarcinoma (1); anemia (1); asthma (1); B-cell acute lymphoblastic leukemia (1); basal cell carcinoma (1); cervical dysplasia (1); chronic lymphatic leukaemia (1); Cirrhosis (1); co-infection (1); colonic polyps (1); Crohn disease (1); cutaneous melanoma (1); diabetes (1); Ductal Breast Carcinoma (1); emphysema (1); familial colorectal cancer type X (1); familial hypercholesterolemia (1); Fanconi anemia complementation group A (1); Fanconi anemia complementation group D2 (1); fibrosis (1).
A further 20 diseases each share a sentence with BARD1 in 1 paper.